ATM (ATM serine/threonine kinase)
Diseases named in the same sentence as ATM in open-access papers (continued):
Sharing a sentence is not in itself a finding about the gene and the disease.
metastatic disease (24 papers, 2016 to 2025). "On the other hand, we documented 3D clusters of pathogenic germline, recurrent somatic variants from primary and metastatic tumours, and hotspots positions in ATM and BRCA2." (PMID 34253785, 2021). "ATM staining was also assessed for correlation with other factors associated with metastatic disease, including tumor cell type, ciliary body involvement, tumor size, inflammatory cell infiltration and mitotic count." (PMID 32481544, 2020). "Addressing this and other outstanding questions using genome-wide approaches is necessary to understand how ATM deficiency increases pancreatic metastatic disease." (PMID 28894253, 2017). "Both germline and somatic ATM mutations are also associated with metastatic disease." (PMID 40046829, 2025). "BRCA2/ATM carriers were found to have more aggressive features of PrCa at diagnosis: Gleason score 8–10 (88.9% vs 59.5%), metastatic disease at diagnosis (80% vs 52.2%) and higher median PSA at diagnosis (59.0 vs 38.4)." (PMID 39516637, 2024). "The inclusion of germline genetic testing for variants in genes such as BRCA1/2, ATM and CHEK2 are likely to be incorporated into mainstream testing for men presenting with locally advanced or metastatic disease." (PMID 33486571, 2022). "CCFs for PPP1R15A or ATM are the same or higher for all metastatic tumors compared to the periocular tumor, further suggesting that this lesion is a direct extension of the primary lesion." (PMID 34400647, 2021). "We also show that there are hotspots in the structures of ATM and BRCA2 proteins where pathogenic germline, and recurrent somatic variants from primary and metastatic tumours, cluster together in 3D." (PMID 34253785, 2021). "The number of white-tan nodules of metastatic tumor counted by naked eyes dropped when ATM was knocked down." (PMID 27556690, 2016). "Strikingly, ATM is the only cell cycle checkpoint kinase gene enriched for mutation in the primary setting, as both CHEK2 (P = 0.001) and ATR mutations (P = 0.0002) are enriched in metastatic disease." (PMID 37390209, 2023). "Loss of function of BRCA1/2, ATM (a DNA-damage checkpoint indirectly activating HRR), and other HRR genes are associated with more aggressive PCs (higher Gleason score; lymph node involvement, and/or metastatic disease at presentation; worse CSS/MFS)." (PMID 35203446, 2022). "Priority genes to test for metastatic disease treatment included BRCA1, BRCA2, and dMMR genes, whereas broader testing such as ATM is reserved for clinical trial eligibility." (PMID 33801751, 2021).
triple-negative breast carcinoma (24 papers, 2014 to 2025). An invasive breast carcinoma which is negative for expression of estrogen receptor (ER), progesterone receptor (PR), and human epidermal growth factor receptor 2 (HER2). "It has been reported that an aberrant decline or loss of ATM was identified in ER/PR/ERBB2-triple-negative breast cancer." (PMID 38027164, 2023). "To test this, we looked for an association between survival of patients with early triple negative breast cancer and phospho-ATM expression in their tumor tissue." (PMID 27613518, 2016). "Our results suggest that ATM negative regulation of MHC-I is a key mechanism of immune escape in triple-negative breast cancer." (PMID 40825766, 2025). "In conclusion, ATM knockdown upregulates HLA expression in triple-negative breast cancer through activation of the c-Jun/TNF-α/p-STAT1 signaling pathway." (PMID 40825766, 2025). "An abnormally low level of ATM was discovered in epidermal growth factor receptor 2 (ErbB2)-triple-negative breast cancer, suggesting the possible regulatory relationship between ATM and ErbB2." (PMID 38027164, 2023). "We show that ATM inhibition enhanced the sensitivity of triple-negative and non-triple-negative breast cancer cell lines to Olaparib, and 53BP1 knock-down partially reversed this effect." (PMID 27613518, 2016). "Immunohistochemistry of FFPE tumor samples from 73 patients with early triple-negative breast cancer identified low expression levels of phospho-ATM in 44 (60.3 %) and high levels in 29 (39.7 %)." (PMID 27613518, 2016). "For instance, ATM negatively regulates PD-L1 expression in triple-negative breast cancer (TNBC) via the JNK/c-Jun/TNF-α signalling axis, suggesting that ATM inhibition could enhance the efficacy of immune checkpoint therapy in PD-L1-negative TNBC patients." (PMID 40256842, 2025). "Other inhibitors, like KU-59403, specifically enhance the effects of topoisomerase poisons in colon cancer, while AZ31 and AZD0156, dual ATM/ATR inhibitors, exhibit synergy with chemotherapy in colorectal and triple-negative breast cancer." (PMID 40256842, 2025). "Interestingly, the ATR inhibitor AZD6738 is in clinical trials in combination with olaparib in triple-negative breast cancer, suggesting that the effects of PARP inhibitors in combination with ATR inhibitors could be tested in patients with ATM-deficient tumours." (PMID 31481733, 2019). "We show that inhibiting ATM increased cytotoxicity of PARP inhibitor in triple-negative and non-triple-negative breast cancer cell lines, and depleting the cells of 53BP1 reduced this cytotoxicity." (PMID 27613518, 2016). "Age-specific distributions of oestrogen-receptor-negative and triple-negative breast cancer status for pathogenic variant carriers in these genes and CHEK2 and ATM were also incorporated." (PMID 36162851, 2022). "Further, overall survival was significantly better in triple-negative breast cancer patients with lower levels of phospho-ATM and tended to be better in patients with negative 53BP1." (PMID 27613518, 2016).
metastatic prostate carcinoma (22 papers, 2017 to 2026). A carcinoma that arises from the prostate gland and has spread to other anatomic sites. "SMARCB regulates transcription through chromatin remodeling, and ATM is a DNA damage repair enzyme altered in up to 10 % of metastatic prostate cancer cases." (PMID 40124187, 2025). "Our cohort included 23 metastatic prostate cancer samples with germline and/or somatic BRCA2d, 10 with CDK12d, 16 with MMRd, and 6 with ATM defects (ATMd)." (PMID 36914848, 2023). "In metastatic prostate cancer, an expanded HRD panel included patients with mutations to BRCA1, BRCA2, ATM, FANCA, CHEK2, PALB2, NBN, or HDAC2." (PMID 35205643, 2022). "The genes containing the highest number of protein-truncating variants in men with metastatic prostate cancer were BRCA2, ATM, and NBN." (PMID 33804961, 2021). "A recent phase II trial of patients with metastatic prostate cancer demonstrated increased sensitivity of patients with ATM aberrations to a poly(adenosine diphosphate [ADP]-ribose) polymerase (PARP) inhibitor." (PMID 28055970, 2017). "There were 280 metastatic prostate cancer samples tested with 11 (4%) somatic BRCA2 and 7 (2.7%) somatic ATM identified with 1 somatic BRCA1." (PMID 40046829, 2025).
sarcoma (22 papers, 2007 to 2025). A usually aggressive malignant neoplasm of the soft tissue or bone. "Although BRCA mutations are rare in sarcomas, alterations in ATM and NF1 have been reported in myxofibrosarcoma, suggesting a potential therapeutic vulnerability." (PMID 41200607, 2025). "We found that among sarcoma and renal cell carcinoma patients diagnosed with a hereditary cancer susceptibility syndrome, the prevalence of a germline ATM pathogenic variant was 2.4% and 6.5%, respectively." (PMID 36865800, 2023). "Studies conducted by Moding and colleagues demonstrated this by using a dual-recombinase ataxia telangiectasia mutated (ATM)-knockout mouse model to show the effects of single-dose radiotherapy and fXRT in a primary sarcoma model." (PMID 37278613, 2023). "Exposure of sarcoma cells to [pazopanib + entinostat] caused activation of ATM, AMPK, and ULK-1 S317 phosphorylation." (PMID 31380285, 2019). "ATM loss has been reported in several sarcoma subtypes, such as leiomyosarcoma and rhabdomyosarcoma." (PMID 28399901, 2017). "Here we present six novel cases of individuals with carcinomas of the gallbladder, uterus, duodenum, kidney, and lung as well as a sarcoma, all harboring germline ATM pathogenic variants, which suggests further expansion of the ATM-associated cancer susceptibility phenotype." (PMID 36865800, 2023). "In cases where there is a known increased risk of developing sarcoma (such as inherited mutations of the ataxia telangiectasia mutated [ATM] gene), women may choose to have a mastectomy instead of breast-conserving surgery to avoid adjuvant radiotherapy." (PMID 37568749, 2023). "The next most frequently mutated genes included CHEK2 (1.4%), ATM (1.2%), and MUTYH (1.2%), with the remaining DDR pathway genes altered in less than 1% of all sarcomas." (PMID 40563612, 2025). "In this study, the second hit approach suggested ATM and POLG as new candidates for association with sarcoma and identified a potential association between KCNQ1 and desmoid fibromatosis." (PMID 39594770, 2024). "This strongly suggests that activation of ATM plays a critical role in mediating the biological actions of 602 in sarcoma." (PMID 32983965, 2020). "We describe the dynamics of these phosphorylations in PBMCs exposed to chemotherapeutic agents and DNA repair inhibitors in vitro, and show that ATM serine-1981 phosphorylation is increased in PBMCs in sarcoma patients treated with doxorubicin in vivo." (PMID 26097887, 2015). "We explore the dynamics of these phosphorylations in PBMCs exposed to chemotherapeutic agents and DNA repair inhibitors in vitro, and show that ATM serine-1981 phosphorylation is increased in PBMCs in sarcoma patients treated with DNA damaging chemotherapy." (PMID 26097887, 2015). "Furthermore, treatments with curative doses of 50 Gy and 80 Gy/4F were capable of inducing growth delays and local control in primary sarcomas, but showed no enhanced cell death when comparing mice with a single ATM allele present to an ATM deletion." (PMID 37278613, 2023). "56.6% of all analyzed sarcoma samples carried alterations in HRR pathway genes; BRCA2, FANCA, and ATM were found among the top altered genes in 11, 10, and 8% of all cases, respectively." (PMID 36779660, 2023).
sarcoma (continued). "Vice versa, all patients with a germline hit considered “second hit not expected” (in genes without a previously known association with mesenchymal tumors or sarcoma), except for CDC73 and ATM, had no second hit." (PMID 39594770, 2024). "Both germline and somatic hits were found in the ATM, CDC73, MLH1, MSH6, POLG, and KCNQ1 genes, which have no previously known connection with sarcoma." (PMID 39594770, 2024).
breast and ovarian cancer (21 papers, 2006 to 2026). "For instance, the ATM gene is well-known as the third most frequently mutated gene in hereditary breast and ovarian cancer (HBOC) after BRCA1 and BRCA2." (PMID 41022541, 2025). "It is estimated that 0.5% to 1% of the general population are HetAT, and studies conducted in hereditary breast and ovarian cancer (HBOC) families or early-onset BC cases showed that deleterious ATM alleles confer a two- to four-fold increase in BC risk for carriers as compared with non-carriers." (PMID 29665859, 2018).
thymic lymphoma (21 papers, 2007 to 2024). "Usually, Atm-deficient mice die from thymic lymphomas at the age of 3-6 months, but however, bone marrow transplantation with ATM-competent cells leads to a stable chimerism and prevents tumorigenesis and prolongs the lifespan of the animals significantly." (PMID 34267759, 2021). "It has also been previously reported that ATM deficiency can be linked to aberrant double-strand DNA repair and chromosomal alterations leading to thymic lymphoma development." (PMID 33046701, 2020). "Therefore, thymic lymphomas in Brca1−/−;Trp53bp1−/− mice are unlikely caused by ATM-dependent signaling defects." (PMID 32139898, 2020). "In line with this hypothesis, treatment of ATM-deficient mice with scavengers of reactive oxygen species (ROS) alleviates the lymphocyte developmental defects observed in these mice, as well as the development of thymic lymphomas." (PMID 26544571, 2015). "Loss-of-function mutation in ATM is one of the causes of cancer, and ERK5 deletion in ATM-/- mice has been shown to delay tumorigenesis and increase response to DNA-targeting agents via H2AX phosphorylation in thymic lymphoma." (PMID 33572742, 2021). "The absence of ATM in humans and mice increases the incidence of tumors of predominantly lymphoid origin, with most tumors appearing in Atm−/− mice being thymic lymphomas." (PMID 27793024, 2016). "Bcl11b is a transcription factor important for T cell development and also a tumor-suppressor gene that is hemizygously inactivated in ~10% human T cell acute lymphoblastic leukemia (T-ALL) and several murine T-ALL models, including ATM(-/-) thymic lymphomas." (PMID 26219558, 2015). "Whereas ATM-/- mice developed thymic lymphomas, the compound mutant mice developed splenomegaly marked by an accumulation of CD3+ cells that were of a CD4+ subtype." (PMID 26544571, 2015). "Reducing mitochondrial ROS by mCAT in ATM-/- mice reduced propensity to develop thymic lymphoma, improved bone marrow hematopoiesis, and macrophage differentiation in vitro, and partially rescued memory T-cell development." (PMID 24860647, 2014). "Circumstantial evidence suggested a link between Myc and ATM, since ATM-/- thymic lymphomas developing in mice ATM-/- are frequently characterized by extra copies of chromosome 15, where the c-myc gene maps." (PMID 22373487, 2012). "In ATM−/− mice heterozygous loss of BCL11B reduced lethal thymic lymphoma by suppressing lymphoma progression but not initiation." (PMID 39295773, 2024). "ATM null mice (ATM-/-) develop thymic lymphomas, despite very mild neurodegenerative phenotypes." (PMID 24860647, 2014). "ATM−/− mice mainly developed thymic lymphoma through an aberrant T cell receptor alpha/delta rearrangement and gene amplification, whereas AML is a clonal disease originated from stem cell and/or progenitor cell that often associated with genomic aberrations and chromosomal rearrangement." (PMID 24474198, 2014). "In addition, double knockout of ATM and Wip1 in mice rescues several phenotypes observed in ATM-null mice, such as thymic lymphomas, possibly due to enhanced DDRs caused by Wip1 depletion." (PMID 23386996, 2013).
Hereditary breast cancer (20 papers, 2008 to 2024). Breast carcinoma that has developed in relatives of patients with history of breast carcinoma. "The discovery of biological pathways enriched for germline and somatic mutations including the role of BRCA1 in DNA repair, ATM, hereditary breast cancer, and DNA damage checkpoint signaling pathways is of particular interest." (PMID 30909550, 2019). "On the other hand, our finding of stronger statistical evidence for genes known to be associated with hereditary breast cancer (CHEK2, ATM and BRCA2) is novel." (PMID 36816149, 2023). "There are also associations of CPT-1A with the wild-type variants of moderate to highly penetrant genes e.g. BRCA1, BRCA2 and ATM involved in hereditary breast cancer." (PMID 36180554, 2022). "For SNV analysis, we identified 16 overlapping pathways in CTCs and metastases involved in the role of BRCA1 in DNA damage response, hereditary breast cancer signaling, and ATM signaling." (PMID 32650480, 2020). "Of note, we found 16 overlapping pathways in CTCs and metastases primarily involved in the role of BRCA1 in DNA damage response, hereditary breast cancer signaling, ATM signaling, and several others." (PMID 32650480, 2020). "In HepG2, only three CPs showed higher –log (p-value) than that of HCT116, and these include “hereditary breast cancer signaling”, “ATM signaling” and “NRF2-mediated oxidative stress response”." (PMID 30042885, 2018). "When pathogenic/likely pathogenic mutations were aggregated within each gene, the association was confirmed for three genes in the UKB at p < 0.0056 (Bonferroni correction for nine tests), including CHEK2, ATM and BRCA2, all also known to be associated with hereditary breast cancer." (PMID 36816149, 2023). "The down-regulated genes were primarily clustered in the cell cycle processes (including cell cycle checkpoints, mitotic assembly and DNA duplication), the DNA repair pathways (including BRCA1 in DNA damage response and ATM signaling), protein ubiquitination and hereditary breast cancer signaling." (PMID 23110199, 2012). "The top pathways included hereditary breast cancer, role of BRCA1 in DNA damage response, molecular mechanisms of cancer, and ATM and GP6 signalling pathways." (PMID 32724790, 2020). "This family member was affected with ductal breast cancer rather than lobular breast cancer and also carried the same ATM PGV." (PMID 33763779, 2022).